MYC (MYC proto-oncogene, bHLH transcription factor)
Diseases named in the same sentence as MYC in open-access papers (continued):
Sharing a sentence is not in itself a finding about the gene and the disease.
Obesity (44 papers, 2013 to 2026). Accumulation of substantial excess body fat. "A recent study demonstrates that obesity can induce the expression of PD-1 on tumor-associated macrophages, which is mediated by the activation of mechanistic target of rapamycin (mTOR) and MYC (MYC proto-oncogene, bHLH transcription factor)." (PMID 40863244, 2025). "One research indicated that EBV infection induces fat mass and obesity-associated gene (FTO) expression through myelocytomatosis oncogene (MYC), inhibiting the translation of m6A-modified metastasis-related genes, thereby reducing lymph node metastasis." (PMID 41573653, 2025). "BMI in our studied population showed a direct relationship with the transcriptional changes (downregulated) observed on selected genes (APC, ARNT, CYP2D6, LEPR, LRP12, and MYC), all of which are closely linked to the development of cancer or obesity." (PMID 35420343, 2022). "Our results showed that MYC was associated with obesity and fatty metabolism." (PMID 36120320, 2022). "The association of high-MYC tumors and obesity may provide the beginnings of a molecular explanation for the rising incidence of EOCRC in developed countries, which also display increasing rates of obesity." (PMID 36139061, 2022). "Pathway enrichment analysis showed marked downregulation of oxidative phosphorylation, MYC targets, G2/M checkpoint regulation, and fatty acid metabolism in obesity." (PMID 41077621, 2026). "Inhibits the MYC/PI3K/AKT signaling pathway by targeting the fat mass and obesity-associated protein." (PMID 40805141, 2025). "We found that MORC3, NUP62, CGAS, ABI3, and RPA2 were highly expressed in lean individuals, where as LMNA, ID2, CDKN1A, TENT4B, MME, and MYC were upregulated in the PBMCs of individuals with obesity." (PMID 40847086, 2025). "Overall, MYC plays multiple roles in obesity, including the maturation of progenitor cells, fatty acid metabolism and extracellular matrix remodelling." (PMID 38510176, 2024). "Intestinal MYC is also increased in humans and mice with obesity, likely due to activation of the ß-catenin pathway, of which MYC is a downstream target." (PMID 38510176, 2024). "Alb-myctg mice overexpress MYC in hepatocytes, and at 36 weeks, they spontaneously develop metabolic syndrome, characterised by obesity, hypertriglyceridemia, hyper-cholesterolemia, glucose intolerance and insulin resistance." (PMID 38510176, 2024). "In this case, its inhibition has been tested: intestinal-specific MYC disruption protected mice subjected to a high-fat diet against obesity, insulin resistance, hepatic steatosis and fibrosis." (PMID 38510176, 2024). "Lowering MYC levels in obese mice had beneficial effects on HFD-induced obesity, IR, steatosis and steatohepatitis." (PMID 38813101, 2024). "Gut dysbiosis increases intestinal MYC expression, facilitating obesity by decreasing GLP-1 secretion and stimulating ceramide synthesis, leading to hypertension." (PMID 37273529, 2023). "Overall, YAP can aggravate intestinal diseases and obesity by promoting the expression of high-affinity AATs and MYC." (PMID 38130953, 2023). "Afterward, based on TFEA and qRT-PCR verification, we confirmed that SOCS3, ICAM-1, NT5E, MYC, CCL2, and PPARG were potential ORDEGs that linked obesity and OLF pathogenesis." (PMID 35712246, 2022). "It was recently found that the transcriptional regulator MYC also interferes with ceramide production, thus modulating intestinal and systemic ceramide levels in obesity." (PMID 35789435, 2022). "Similar to RBM15, HNRNPC, and HNRNPA2B1, MYC expression level significance was also negatively related to obesity." (PMID 36120320, 2022). "We have previously demonstrated that obesity-mediated by high-fat diet and deficiency in FOXO3 leads to LDs accumulation and activates MYC in mouse colon." (PMID 34845203, 2021). "We found that c-MYC transgenic mice with ageing are prone to develop obesity, metabolic syndrome (MS), and abnormal accumulation of lipids in the liver compared to control mice." (PMID 35008356, 2021).
Obesity (continued). "CEBPα regulates transcription of the human fat mass and obesity-associated gene (FTO), and c-MYC is well known for its role in cancer metabolism." (PMID 26109058, 2015). "Therefore, an intestine-specific decrease in MYC expression in mice can ameliorate high-fat diet-induced obesity, insulin resistance, hepatic steatosis, and steatohepatitis." (PMID 38130953, 2023). "Lastly, our results suggest an obesity‐related regulatory switch involving two transcription factors, MYC and FOS, which may drive the distinctive endotypes we observe." (PMID 37006170, 2023). "The increased expression of intestinal MYC was observed in both obese people and mouse models, suggesting that intestinal MYC may be involved in the development of obesity-related metabolic syndrome." (PMID 36594091, 2023). "In addition, obesity has been shown to increase intestinal MYC expression through the Wnt/β-catenin pathway." (PMID 36139061, 2022). "Although FXR, HIF2a, and MYC alter ceramide formation through unique processes, each system promotes the delivery of ceramides from the intestine to other tissues, including the liver, thereby impairing systemic metabolic integrity in obesity." (PMID 35789435, 2022). "Therefore, obesity may be contributing to MYC activity and tumorigenesis in EOCRC in part through the UPR." (PMID 36139061, 2022). "PTEN deficiency leads to hyperproliferation and probably plays a permissive role in carcinogenesis; additional events, usually in form of second mutation [e.g., in MYC gene], is needed for malignant transformation—this is possible even in the absence of obesity." (PMID 32582754, 2020). "c-MYC induces DNA damage and increases ROS levels by activating the cGAS-STING signaling pathway, as observed in obesity and metabolic syndrome." (PMID 38813101, 2024). "Using the same Hi-MYC mouse model, Blando and coworkers also showed that HFD-induced obesity enhances, whereas 30% caloric restriction reduces growth factor (AKT/mTORC1 and STAT3) and inflammatory (NFκB and cytokines) signaling and PCa progression." (PMID 34386430, 2021). "In Hi-MYC mouse model, HFD-induced obesity (enriched for SFA) amplifies a c-MYC-mediated oncogenic transcriptional signature, which is associated with lethality in patients." (PMID 34386430, 2021). "Subsequently, abundant intestinal MYC targets ceramide synthase 4 (Cers4) to stimulate ceramide synthesis and simultaneously decrease glucagon-like peptide 1 (GLP-1) secretion, facilitating obesity." (PMID 37273529, 2023). "Thus, it is plausible that the FOXO3 and LDs regulatory network, facilitated by obesity, may involve ATGL and MYC." (PMID 34845203, 2021).
renal cell carcinoma (44 papers, 2008 to 2025). "For example, in renal cell cancer, pontin knockout led to a decreased mRNA of both MYC and Cyclin D1, associated with a decrease of nuclear β-catenin expression." (PMID 32517078, 2020). "Especially in human renal cell carcinoma, MYC is frequently mutated or overexpressed." (PMID 37047552, 2023). "This study reveals that circPVT1 promotes the renal cell carcinoma lung metastasis and tumor progression through encoding the cP104aa peptide and directly binds with EIF4A3, which jointly regulates the target gene c‐MYC." (PMID 40966379, 2025). "A separate study demonstrated that co-culturing renal cell carcinoma (RCC) cells with neutrophils can specifically impact MYC signaling, thereby promoting RCC cell proliferation." (PMID 40732268, 2025). "DEGs within the MYC + Epithelial subcluster showed significant enrichment in pathways including Renal Cell Carcinoma, PI3K-Akt, and HIF-1 signaling." (PMID 38802480, 2024). "First off, the GLUD1 protein levels have been characterized as being elevated in MYC-induced murine renal cell carcinoma." (PMID 34503295, 2021). "So, while HIF-1α antagonizes c-MYC-induced proliferation, HIF-2α increases it by potentiating the oncogenic effect of c-MYC in an in vitro model with VHL-deficient renal cell carcinoma." (PMID 30939818, 2019). "Renal cell carcinomas with VHL deficiency and c-MYC amplification exhibit HIF-2α stabilization and PLA2R1 repression by promoter hypermethylation." (PMID 30939818, 2019). "MYC activation plays a central role in and its overexpression drives renal cell carcinoma." (PMID 38288105, 2023). "GLS2 proteins were also downregulated in MYC-induced renal cell carcinoma." (PMID 34503295, 2021). "Moreover, miR-135a has been reported as a tumor-suppressive factor that inhibits cancer cell proliferation by targeting c-MYC in renal cell carcinoma." (PMID 25888950, 2015).
oral squamous cell carcinoma (43 papers, 2009 to 2026). "Aberrant expression or amplification of the MYC gene has been observed in oral squamous cell carcinoma (OSCC) and is associated with tumor development and progression." (PMID 37893092, 2023). "Our results revealed a previously uncharacterized regulatory axis in NPC that is distinct from the METTL3-YTHDF1-c-MYC pathway reported in oral squamous cell carcinoma." (PMID 41167308, 2025). "Consistent with our findings, recently Sabit and coworkers showed that the knockdown of MYC controls the proliferation of oral squamous cell carcinoma cells in vitro by regulating key apoptotic marker genes." (PMID 37444499, 2023). "Similarly, a study observed over expression of c-MYC in established oral squamous cell carcinoma when compared to oral epithelial dysplasia." (PMID 36985413, 2023). "Similarly, one report showed that silencing CD47 decreased MYC expression in oral squamous cell carcinoma, which indicates that CD47 can increase MYC expression." (PMID 36966168, 2023). "Accordingly, in oral squamous cell carcinoma, METTL3 can collect the m6A reader YTHDF1 to facilitate their target c-MYC transcript stability." (PMID 37259333, 2023). "Experimentally, MYC could accelerate TGF-β1 transcription and promote oral squamous cell carcinoma tumorigenesis." (PMID 39113693, 2024). "Likewise, Tanshinone IIA (Tan IIA) suppresses HK-mediated glycolysis of oral squamous cell carcinoma (OSCC) cells by promoting FBXW7-mediated degradation of c-MYC and inhibiting the AKT-c-MYC signaling, exhibiting its natural antitumor activity." (PMID 35515121, 2022). "Additionally, METTL3 could enhance the stability of c-MYC through YTHDF1-mediated m6A modification and promote tumorigenesis in oral squamous cell carcinoma." (PMID 36675186, 2023). "This multi-layered regulation is absent in oral squamous cell carcinoma, where YTHDF1-mediated regulation of c-MYC is limited to mRNA stability without evidence of translational coordination or nuclear export involvement." (PMID 41167308, 2025).
head and neck squamous cell carcinoma (40 papers, 2015 to 2026). A squamous cell carcinoma that arises from any of the following anatomic sites: lip and oral cavity, nasal cavity, paranasal sinuses, pharynx, larynx, and salivary glands. "Exposure to nicotine and acrolein, which are the risk factors for the occurrence of head and neck squamous cell carcinomas (HNSSCs), was shown to increase both MYC Proto-Oncogene Protein (c-MYC) and BRAF." (PMID 35268568, 2022). "Similarly, studies have shown that the MYC gene is frequently amplified in head and neck squamous cell carcinoma (HNSCC), contributing to tumor progression." (PMID 40182194, 2025). "Recent studies highlight MYC overexpression as a potential biomarker and therapeutic target in recurrent and metastatic head and neck squamous cell carcinoma (HNSCC)." (PMID 41295214, 2025). "While the tumorigenic effects of MYC in patients with head and neck squamous cell carcinoma (HNSCC) are well known, the molecular mechanisms by which the amplification of this gene may confer treatment resistance, especially to immune checkpoint inhibitors, remains under-investigated." (PMID 38783041, 2024). "In patients with head and neck squamous cell carcinoma (HNSCC), upregulation of CALM1, CYCS, THBS1, MYC, GATA6, and SPRED3 was strongly associated with a poor prognosis." (PMID 36239104, 2022). "In head and neck squamous cell carcinoma (HNSCC), TRMT61A-mediated tRNA m1A58 modification directly regulates the translation of MYC mRNA through codon decoding, thereby affecting tumor occurrence and development." (PMID 41501031, 2026). "MYC/MAX was a hub regulator of LINC00958, which is consistent with the results of studies on head and neck squamous cell carcinoma cells." (PMID 35223488, 2022). "For instance, AFF4 could upregulate SOX2 transcription to promote the tumor-initiation capacity of head and neck squamous cell carcinoma (HNSCC), and MYC is another known target of AFF4." (PMID 32676121, 2020). "Moreover, in head and neck squamous cell carcinoma (HNSCC), therapeutic inhibition of MYC promoted intrinsic anti-tumor immune responses through the cGAS-STING signaling pathway, and CD8+ T-cell infiltration of HNSCC in vivo." (PMID 38390324, 2024). "Interestingly, the expression of the transcription factor MYC was downregulated in the presence of IL-33 in SCC-25 and Detroit 562 cells, two head and neck squamous cell carcinoma (HNSCC) cell lines." (PMID 38662248, 2024). "In colon and head and neck squamous cell carcinomas, overexpression of CIP2A leads to the potentiation of MYC S62 phosphorylation, the PP2A target, thereby inhibiting proteolysis and resulting in increased oncogenic MYC protein stability." (PMID 25699237, 2015).
squamous cell carcinoma (38 papers, 2009 to 2025). A carcinoma arising from squamous epithelial cells. "Here, we show that Serine 62 phosphorylation, which increases MYC stability and oncogenic activity, is elevated while Threonine 58 phosphorylation, which targets MYC for degradation, is decreased in squamous cell carcinoma (SCC)." (PMID 32895364, 2020). "A recent publication also confirmed that MYC is a key downstream target of BRD4-NUT, associated with an aggressive form of squamous cell carcinoma." (PMID 25989842, 2015). "In addition, strong nuclear MYC expression throughout squamous cell carcinoma is a critical feature for KPU-driven LUSC." (PMID 38093367, 2023). "Similarly, in Ad5-CC10-Cre-infected KPU mice, MYC was translocated into the nucleus at the squamous CIS lesion, and the strong nuclear expression of MYC persisted during squamous carcinoma development." (PMID 38093367, 2023). "With respect to epithelial neoplasms, MYC amplification has been reported in approximately 50% of squamous cell carcinomas from immunosuppressed patients following organ transplantation, and diffuse nuclear MYC immunolabeling has been demonstrated in eyelid sebaceous carcinomas." (PMID 34445161, 2021). "Notably, MYC/myrAKT1-transduced basal or luminal cell derived organoids developed tumors composed of a mixture of adenocarcinoma with squamous cell carcinoma or adenosquamous carcinoma in vivo, respectively." (PMID 28881646, 2017). "Concretely, Epi2_MUC5B represented adenocarcinoma cell (MUC5B, MUC16, MUC5AC), while Epi4_MYC harbored conventional squamous cell carcinoma features, such as high expression of KRT6A and MYC." (PMID 40657372, 2025). "High frequency of mutations in HRAS, copy number alterations and aberrant expression levels in KRAS, NRAS, MYC and EGFR have been reported in relation with development of many squamous cell carcinomas." (PMID 34796107, 2021). "The high numbers of MYC and EGFR variations in PSCC are in concordance with previous evidence reported in head and neck cancers squamous cell carcinoma, a similar tumor with dual pathogenesis." (PMID 35008677, 2021). "The gene copy ratio of MYC and CDKN2A in the same pattern has a prognostic value in squamous cell carcinoma of the head and neck." (PMID 24675718, 2014). "In squamous cell carcinoma, USP28 is strongly expressed and stabilizes the essential squamous transcription factor ΔNp63, together with important oncogenic factors, such as NOTCH1, c-MYC and c-JUN." (PMID 34685632, 2021). "Similar to MYC, CCND1 is frequently amplified in the squamous cell carcinoma." (PMID 32405341, 2020). "TGF-β and MYC were usually overexpressed among the squamous carcinoma, but not progenitor carcinoma." (PMID 31521140, 2019).